SNORA23 (small nucleolar RNA, H/ACA box 23)
Synonyms: ACA23
Gene: Small nucleolar RNA gene on chromosome 11 (9,428,773 to 9,428,954, forward strand). Ensembl gene ENSG00000201998.
Gene Ontology:
Biological process: RNA processing
Cellular component: nucleolus
Homologues: Orthologues: chimpanzee SNORA23 (98% identical), macaque SNORA23 (98% identical), guinea pig SNORA23 (89% identical), mouse Snora23 (87% identical), rat Snora23 (86% identical), zebrafish SNORA23 (66% identical).
Diseases named in the same sentence as SNORA23 in open-access papers:
SNORA23 is named in the same sentence as 6 diseases in open-access papers, as found by Europe PMC text mining. Sharing a sentence is not in itself a finding about the gene and the disease. The quoted sentences say what the papers report.
glaucoma (3 papers, 2012 to 2023). Increased pressure in the eyeball due to obstruction of the outflow of aqueous humor. "Additionally, SNORD3A, SNORD16, SNORA52, and SNORA23 were differentially expressed in patients with glaucoma." (PMID 37805546, 2023).
pancreatic ductal adenocarcinoma (2 papers, 2020 to 2021). An infiltrating adenocarcinoma that arises from the epithelial cells of the pancreas. "A previous study showed that SNORA23 is upregulated in pancreatic ductal adenocarcinoma (PDAC) tissues and cell lines." (PMID 33710804, 2021).
glioblastoma (1 paper, 2015). The most malignant astrocytic tumor (WHO grade IV). "Among the ten most upregulated genes, five (SNORA20, SNORA71A, SNORA23, SNORA3, SNORA68) were recently found to be downregulated by HOXA10 in LN18 glioblastoma cells." (PMID 26362268, 2015).
schizophrenia (1 paper, 2019). A major psychotic disorder characterized by abnormalities in the perception or expression of reality. "Although non-coding RNAs such as small nucleolar RNAs (snoRNAs), microRNAs and long non-coding RNAs (LncRNAs), have been studied in disease etiology, the involvement of SNORA38B, SNORA68, SNORA23, SNORA20, and SNORA3A in the pathogenesis of schizophrenia has yet to be reported." (PMID 30967896, 2019).
tumor (2 papers, 2021 to 2025). "Expression of SNORA23 was low in both HCC tumor tissues and cell lines, and correlated with poor prognoses of HCC patients." (PMID 33710804, 2021). "Only the expression of SNORA23 was inhibited in HCC, indicating the tumor suppressor role of SNORA23." (PMID 33710804, 2021). "In our study, we identified SNORA23 as a downstream factor of PI3K/AKT/mTOR signaling and showed that SNORA23 played a tumor suppressor role in HCC." (PMID 33710804, 2021). "SNORA23 is directly affected by the PI3K/AKT/mTOR cascade and acts as a tumor suppressor in HCC; thus, we next aimed to determine the effect of SNORA23 on downstream regulators of PI3K/AKT/mTOR signaling by using Western blot." (PMID 33710804, 2021).
SNORA23 also shares sentences with these, for which no sentence is quoted: pancreatic cancer (1 paper).